ABO (ABO, alpha 1-3-N-acetylgalactosaminyltransferase and alpha 1-3-galactosyltransferase)
Diseases named in the same sentence as ABO in open-access papers (continued):
Sharing a sentence is not in itself a finding about the gene and the disease.
gastric cancer (26 papers, 2004 to 2025). A primary or metastatic malignant neoplasm involving the stomach. "The results of this study revealed significant associations between ABO blood groups and various clinical and pathological features of gastric cancer, including disease risk, tumor localization, and histological subtype." (PMID 41030727, 2025). "There are few studies on the diagnostic value of ABO blood group combined with tumor markers for gastric cancer." (PMID 38213731, 2024). "Another single-center study in China demonstrated that there exist association between ABO blood group and the risk of incidence of gastric cancer." (PMID 36181128, 2022). "The association of ABO blood groups with gastric cancer risk was proposed decades ago, but the results have been inconsistent." (PMID 30791881, 2019). "Since then, the association of ABO blood groups and gastric cancer risk has been extensively studied; however, the results have been variable." (PMID 30791881, 2019). "In the case-control study, we used genotype-inferred blood groups which lowered the risk of misclassification from self-report blood type and allowed us to evaluate the associations of ABO genotypes with gastric cancer risk specifically." (PMID 30791881, 2019). "The studies by Aird et al6,14 were the first to report an association between the ABO blood group and both peptic ulcer and gastric cancer." (PMID 29093357, 2018). "Further studies are warranted to delineate the mechanism between ABO blood type and risk of gastric cancer." (PMID 28880901, 2017). "To understand the correlation between ABO blood groups and the risk of developing gastric cancer, we conducted a case-control study of 1,045 cases of gastric cancer from Shanghai Ruijin Hospital, and 53,026 healthy blood donors from Shanghai blood center." (PMID 23202954, 2012). "This study focuses on the association between the ABO blood group system and the risk of gastric cancer or Helicobacter pylori infection." (PMID 23202954, 2012). "We also consider that further studies should be conducted to investigate the relationship of the ABO blood groups with the main risk factors of gastric cancer, such as pernicious anemia, atrophic gastritis, gastric pH, pepsinogen level, and H. pylori infection." (PMID 36788998, 2023). "Therefore, in the current study, we performed a large genetic study to evaluate the associations of ABO blood groups and genotypes with risk of gastric cancer in Chinese populations." (PMID 30791881, 2019). "We used two single nucleotide polymorphisms to determine ABO genotype in 4932 gastric cancer cases and 6158 controls of Chinese descent, and evaluated the associations of ABO blood groups and genotypes with risk of gastric cancer using multivariable logistic regression models." (PMID 30791881, 2019). "Previous studies have demonstrated the association between ABO blood group antigens and clinical outcome in several human cancers, such as esophageal squamous cell cancer, laryngeal cancer, gastric cancer and non-small cell lung cancer." (PMID 29109911, 2017). "Moreover, we searched the Pubmed database and combined them with our own research data in order to perform an overall meta-analysis on the relationship between ABO blood groups and the gastric cancer risk." (PMID 23202954, 2012). "However, the exact molecular mechanism underlying the relationship between ABO blood groups, H. pylori infection and gastric cancer needs to be further explored." (PMID 23202954, 2012). "A study investigating gastric cancer cells reported that the deletion of a downstream region of the ABO gene altered the expression of nearby genes, including a reduction in ADAMTS13 transcription." (PMID 41311061, 2025). "This study found that there were differences in ABO blood group distribution between the gastric cancer group and the healthy control group." (PMID 38213731, 2024).
gastric cancer (continued). "The expression of blood group ABO antigens (BGA) has been reported to decrease in gastritis and gastric cancer, suggesting that the loss of BGA expression in gastric epithelial cells is associated with cell differentiation and precancerous changes." (PMID 37569679, 2023). "We have previously reported that HDACIs such as sodium butyrate and panobinostat suppress ABO expression in the gastric cancer cell line KATOIII19." (PMID 33564039, 2021). "ABO-rs7849280 is a key regulator of host-bacterial interactions of H. pylori-related diseases and gastric cancer." (PMID 34771687, 2021). "The role of ABO blood types in gastric cancer was initially suggested in more than 60 year ago, with the clinical observation that patients with gastric cancer were more likely to have blood group A than controls." (PMID 30791881, 2019). "We attempted to perform potential disease subgroup analyses, however there was an insufficient number of epidemiological papers to see the relationship between H. pylori and ABO amongst PUD or gastric cancer compared to NUD." (PMID 30514875, 2018). "The data for the ABO blood group was collected from 1045 cases of gastric cancer, whereby the patient underwent a gastrectomy in Ruijin Hospital, Shanghai." (PMID 23202954, 2012). "A decrease in blood group ABO antigen expression in gastric cancer has also been reported." (PMID 35176282, 2022). "In addition, past studies had shown that ABO genotype was closely related with gastric cancer development." (PMID 29254216, 2017). "We compared the distribution of ABO blood groups in H. pylori positive cases and H. pylori negative cases in the gastric cancer group." (PMID 23202954, 2012).
coronary artery disease (20 papers, 2012 to 2025). "The ABO gene locus has been identified to be associated with myocardial infarction in patients with coronary heart disease." (PMID 36694759, 2023). "According to the reported studies, ABO has been associated with blood transfusions, organ transplants, and diseases such as cancer, coronary heart disease (CHD), and lower circulating cholesterol levels." (PMID 34812738, 2021). "ABO is a well-known pleiotropic locus associated with coronary artery diseases, type 2 diabetes, liver enzyme levels (alkaline phosphatase) and lipid levels." (PMID 32492067, 2020). "In particular, a variant (rs2519093) of the ABO gene, which is directly associated with concentrations of E-selectin, has direct associations with coronary artery disease, venous thromboembolism, and cardiometabolic risk factors." (PMID 32438708, 2020). "Both the chr9p21 and the ABO locus were independently found to be associated with coronary artery disease, and ABO is also a risk locus for venous thromboembolism." (PMID 27796860, 2016). "The associations between FVIII levels and the ABO gene variant rs505922, and between ABO and coronary disease, suggest a possible mechanism behind the well-documented association between the ABO blood group and risk of vascular disorders." (PMID 23381943, 2013). "In accordance, recently distinct genome-wide association studies linked the ABO gene with MI in the presence of coronary atherosclerosis, with coronary artery disease, with type 2 diabetes and with venous thromboembolism." (PMID 23300549, 2012). "Previous SNP associations in or near ABO are in high linkage disequilibrium with our lead SNP and include associations with inflammatory markers, lipids and haematological parameters as well as diseases such as cancer and coronary heart disease." (PMID 23056639, 2012). "Given the known pleiotropy of ABO, we detected colocalization with several hundred proteins (in trans) as well as clinical traits, most prominently with cardiovascular ones (coronary heart disease, hyperlipidemia, pulmonary heart disease)." (PMID 41325371, 2025). "The genetic locus located within the ABO gene plays a role in hemoglobin concentration, hematocrit, von Willebrand factor, myocardial infection, coronary artery disease, ischemic stroke, type 2 diabetes, and venous thromboembolism." (PMID 35096865, 2021). "In particular, ABO has been reported as protecting against hypertension in a Spanish population, and is related to ischemic heart disease in a Pakistani population." (PMID 27980649, 2016). "Genome-wide association studies (GWAS) identified several single nucleotide polymorphisms (SNPs) associated with coronary artery disease (CAD) and myocardial infarction (MI) locus in ABO gene." (PMID 27542834, 2016). "The present study was designed to explore the relation between ABO blood group and coronary heart disease in Asian Indian Bengali population of eastern part of India." (PMID 23984407, 2013). "The purpose of this study is to establish whether ABO blood group is related to coronary heart disease in an individual in Asian Indian Bengali population of eastern part of India." (PMID 23984407, 2013). "In addition, miR-10b-5p could regulate the formation of coronary artery disease by mediating ABO locus." (PMID 37228823, 2023).
respiratory failure (19 papers, 2020 to 2025). The significant impairment of gas exchange within the lungs resulting in hypoxia, hypercarbia, or both, to the extent that organ tissue perfusion is severely compromised. "Significant increases in dehydration, acute respiratory failure, and ABO isoimmunization were noted during COVID-19 (χ2 = 55.55, df = 10, p < 0.05)." (PMID 41141131, 2025). "During COVID-19, the proportion of readmissions due to dehydration, acute respiratory failure, and ABO isoimmunization increased significantly (χ2 = 55.55, df = 10, p < 0.05)." (PMID 41141131, 2025).
myocardial infarction (17 papers, 2012 to 2025). Gross necrosis of the myocardium, as a result of interruption of the blood supply to the area, as in coronary thrombosis. "For example, the 9q34.2 locus, associated with the ABO blood group, has been directly linked to the incidence of myocardial infarction in subsequent research." (PMID 39960900, 2025). "Some previous studies on Caucasians suggested the correlation of ABO polymorphism and myocardial infarction." (PMID 28811939, 2017). "For instance, the ABO O allele is also associated with a reduced risk of myocardial infarction and pancreatic and skin cancer." (PMID 22291609, 2012). "Recent GWASs have identified ABO as a locus for thrombosis, myocardial infarction, and multiple cardiovascular risk biomarkers, refocusing attention on mechanisms and potential for clinical advances." (PMID 23133757, 2012). "In addition, genome-wide association studies (GWASs) showed that the ABO blood type is not only a risk factor for atherosclerosis but also important in the pathogenesis of acute coronary syndrome and myocardial infarction." (PMID 36299697, 2022). "This specific ABO gene SNP has previously been associated with myocardial infarction." (PMID 34777790, 2021). "Hence, this study was designed to investigate the correlation of ABO polymorphism and thrombomodulin polymorphism −33G>A with the incidence of acute myocardial infarction (AMI)." (PMID 28811939, 2017). "Hence, this study was designed to investigate the correlation of ABO polymorphism and thrombomodulin polymorphism −33G>A with the incidence of acute myocardial infarction in Javanese men." (PMID 28811939, 2017). "Recent studies have confirmed that the ABO locus that encodes for the ABO blood type may be associated with myocardial infarction and venous thromboembolism." (PMID 26860707, 2016). "One of the strongest putatively causal CpG sites in the ABO gene, cg24267699, was shown to be positively correlated with CHD/myocardial infarction risk factors." (PMID 40845133, 2025). "The primary focus of this hospital-based study was to explore the relationship of ABO blood groups and ABO genotypes with acute myocardial infarction (AMI) in Karachi, Pakistan." (PMID 36694759, 2023). "Previous studies have conclusively linked the ABO locus to risk of PC 6, VTE 12, and myocardial infarction in the presence of coronary atherosclerosis." (PMID 26275671, 2015). "Both studies revealed that ABO polymorphism that increases the susceptibility of myocardial infarction in Caucasian population failed to give significant result in China population." (PMID 28811939, 2017). "Chi-square analysis of ABO polymorphism based on O and non-O blood group with the incidence of myocardial infarction showed that both blood groups had similar risk factor of myocardial infarction." (PMID 28811939, 2017). "A GWAS study found that ABO locus showed the top signal for myocardial infarction in patients with angiographic coronary artery disease (CAD), and concluded that the variation linked to group O and reduced vWF, was protective against myocardial infarction in CAD patients." (PMID 25592833, 2015).
Stroke (16 papers, 2013 to 2025). Sudden impairment of blood flow to a part of the brain due to occlusion or rupture of an artery to the brain. "Multiple investigations consistently proved the link between the ABO locus and stroke, with some underscoring its association with the LAA subtype." (PMID 38965603, 2024). "Genetic variants in ABO are associated with various health conditions, such as diabetes, thromboembolism, myocardial infractions, atherosclerosis, and stroke." (PMID 37239387, 2023). "Among the 15 associated variants were two common SNPs in ABO, rs507666 and rs635634 that are in near perfect linkage disequilibrium with each other (r2 = 0.99) and that have previously been associated with stroke." (PMID 36672803, 2022). "We identified 13 rare stroke-associated variants as well as one additional association with 2 common variants at a previously known locus in ABO." (PMID 36672803, 2022). "In particular, our analyses suggest that the ABO blood subgroups A1-tagging and O1-tagging variants (rs529565 and rs635634) are sufficient for capturing nearly all of the ABO-mediated genetic association with early-onset (and perhaps late) stroke." (PMID 36240095, 2022). "We observed genome-wide significant associations of EOS with 2 variants in ABO, a known stroke locus." (PMID 36240095, 2022). "Although our study had limited power to examine stroke subtypes, it is notable that the ABO O1 and A1-defining SNPs were also significantly associated with large artery atherosclerosis, cardioembolic, and undetermined stroke subtypes." (PMID 36240095, 2022). "We identified 15 coding variants significantly associated with all ischemic stroke at array-wide threshold (i.e., p < 4.7 × 10−7), including two common SNPs in ABO that have previously been associated with stroke." (PMID 36672803, 2022). "Stratified analyses indicate that both SNPs are independently associated with stroke, and further association analyses at the ABO locus that condition on the effects of these 2 SNPs reveal only modest additional signal at this locus." (PMID 36240095, 2022). "The associations we observed for these SNPs with EOS are substantially higher than the peak associations previously reported at the ABO locus in predominantly older stroke populations (e.g., OR = 1.08; 95% CI: 1.05–1.11 in MEGASTROKE1)." (PMID 36240095, 2022). "In the meta-analysis of WTCCC2 and MORGAM, SNP rs505922 in the ABO gene was associated with ischemic stroke (beta for T allele = –0.067, p = 0.023), with the major T allele being protective against stroke." (PMID 23381943, 2013). "Interestingly a recent large-scale meta-analysis genome-wide association study (GWAS) identified the A1 blood haplotype variation at the ABO locus to be associated with early-onset IS compared to later-onset strokes." (PMID 37048683, 2023). "For Stroke, there were 3,221 genes and 458 proteins, with 57 overlapping targets at the gene-protein level including ABO, AOC1, and ARL2BP." (PMID 41340073, 2025). "ABO rs505922 has been previously shown to be highly correlated with an increased risk of large artery atherosclerosis (LAA) and cardioembolism (CE) stroke." (PMID 38965603, 2024). "The study combined clinical data with mechanistic validation experiments, unveiling potential mechanisms linking ABO blood type to stroke." (PMID 38965603, 2024). "In blood, we identified 5 genes (MMP12, SCARF1, ABO, F11, and CKAP2) that had causal relationships with stroke and stroke subtypes." (PMID 35449099, 2022). "Specifically, 3 genes have been associated with atherothrombotic stroke subtype (HDAC9, CDKN (locus 9p21) and TSPAN2), 2 genes with cardioembolic stroke subtype (PITX2 and ZFHX3), and 2 genes with young strokes (ABO and MMP12)." (PMID 29321829, 2018). "Most existing research has primarily investigated how the ABO gene affects stroke subtypes." (PMID 38965603, 2024).
Stroke (continued). "To date, a stroke can be genetically associated with multiple susceptibility loci, including 9p21 (CDKN2A/CDKN2B/ANRIL), 7p21 (HDAC9), 6p21.1, 4p25 (PITX2), 16q22 (ZFHX3), 9q34 (ABO)." (PMID 33808851, 2021). "A meta-analysis involving 12 GWAS studies with 10,307 IS patients and 19,326 healthy individuals, conducted in both Caucasian and South Asian populations, established a robust genome-wide link between the ABO locus and the LAA subtype of stroke." (PMID 38965603, 2024). "Eight protein-disease pairs were ranked as the most valuable findings after the filtering, which include IL-7R and TNFSF12 level on asthma; ACE level on COPD; AIF1 level on HF; SERPINF1 level on stroke; and SERPINE2, F11, KLKB1, and ABO level on VTE." (PMID 36388766, 2022). "In the same year, and with a sample size of 16,851 cases and 32,473 non-stroke controls, the NINDS Stroke Genetics Network (SiGN) found a new locus associated with LAS close to TSPAN2 and confirmed the previous loci ABO, HDAC9, PITX2, and ZFHX3." (PMID 35743317, 2022). "Furthermore, 5 different genes (MMP12, ABO, SCARF1, F11, and CKAP2) were discovered in blood, which indicated two distinct pathogenesis for stroke in brain and blood." (PMID 35449099, 2022).